ANXA2 (annexin A2)
Diseases named in the same sentence as ANXA2 in open-access papers (continued):
Sharing a sentence is not in itself a finding about the gene and the disease.
breast carcinoma (continued). "Anxa2 was highly expressed in all the EGFR positive breast cancer cell lines, and strongly positive expression of Anxa2 was found in cell lines that were characterized as mesenchymal-like and highly aggressive, such as MDA-MB-231, MDA-MB-435 and MCF-7/ADR." (PMID 26307676, 2015). "Our findings provide clinical evidence that Anxa2 is a poor prognostic factor for breast cancer and reveal a novel mechanism through which Anxa2 promotes breast cancer metastasis." (PMID 26307676, 2015). "In this study, we observed that EGF induces EMT of breast cancer cells along with constantly tyrosine phosphorylation of Anxa2." (PMID 26307676, 2015). "Together, these evidences suggest that Anxa2 is required for EGF-induced activation of STAT3 in breast cancer cells." (PMID 26307676, 2015). "More interestingly, results from IHC analysis of human breast cancer tissues supported the contribution of Anxa2 to the activation of STAT3." (PMID 26307676, 2015). "In this study, we observed that Anxa2 expression was upregulated in aggressive type of breast cancer tissues, similar to the findings of previous studies." (PMID 26307676, 2015). "Using similar knockdown strategy, we observed that dual depletion of MIEN1 and AnxA2 led to a two-fold decrease compared to siGFP, indicating that MIEN1 and AnxA2 functionally cooperate to promote breast cancer cell migration." (PMID 26272794, 2015). "In breast cancer, AnxA2 mediated plasmin activation is shown to be essential for angiogenesis, migration and invasion which are critical events in disease metastasis." (PMID 26272794, 2015). "We previously showed that upregulated Anxa2 expression promotes the invasion of breast cancer cells, whereas Anxa2 knockdown inhibits cells invasive potential." (PMID 26307676, 2015). "We proved for the first time that the upregulated Anxa2 expression is correlated with cancer metastasis and poor outcomes in breast cancer patients." (PMID 26307676, 2015). "Our findings suggest a novel mechanism through which Anxa2 promotes breast cancer EMT and metastasis." (PMID 26307676, 2015). "Our studies convincingly demonstrate that interaction of MIEN1 with AnxA2 is required for extracellular plasmin generation thereby increasing breast cancer cell migration and invasion." (PMID 26272794, 2015). "Given that STAT3 is a well-known key pathway downstream of EGFR and an EMT promoter in breast cancer, we infer that the possible mechanism through which Anxa2 promotes EMT is dependent on the STAT3 pathway." (PMID 26307676, 2015). "In contrast, overexpression of ANXA2 promotes cell proliferation in lung cancers and inhibits apoptosis in breast cancers." (PMID 24591769, 2014). "Both AnxA2kd and AnxA5kd cells have decreased proliferative capacity compared to Si cells, and suppression of AnxA2 by shRNA similarly decreases proliferation of adenocarcinoma, breast cancer, and multiple myeloma cells." (PMID 25222280, 2014). "Annexin A2 expression also correlated with increased recruitment of inflammatory cells into tumor sites and with elevated neoangiogenic activity in breast cancer patients." (PMID 23519104, 2013). "Our objective is to characterise exosomal AnxA2 and study its role in breast cancer microenvironment." (PMID 26082317, 2013). "Treatment with angiostatin inhibits breast cancer growth and lung metastasis formation via binding to annexin A2 and inhibiting annexin A2-mediated plasmin generation." (PMID 23519104, 2013). "Our finding are consistent with previous reports that have shown annexin A2 neutralizing antibodies to inhibit cell migration, invasion, and to block plasminogen activation of breast cancer cells and monocytes in vitro." (PMID 23945256, 2013). "Annexin A2 is also potentially involved in promoting breast cancer resistance to chemotherapeutic anthracyclines and taxanes." (PMID 23519104, 2013).
breast carcinoma (continued). "In this study, we establish three new findings that elucidate the role of Anxa2 in the proliferation and invasion of breast cancer SK-BR-3 cells, and the effect of Anxa2 on the stimulation of Stat3 pathways." (PMID 23691485, 2012). "Her-2 amplified specimen showed weak staining of AnxA2 (0–1+, 0–10% cells showed very faint staining) while Her-2 null/basal breast cancer specimen demonstrated strong membrane expression of AnxA2 (Figure 1Aii, >3+, >30% cells with strong membranous staining)." (PMID 22957061, 2012). "To study this, we used JIMT-1 cells (isolated from a Herceptin-resistant breast cancer patient) and screened for AnxA2 expression." (PMID 22957061, 2012). "We found an inverse correlation of Her-2 and AnxA2 expression in clinical specimens of breast cancer patients, which was consistent with the expression profile in breast cancer cell lines." (PMID 22957061, 2012). "We report an inverse correlation between Her-2 and AnxA2 in breast cancer clinical samples and cell lines." (PMID 22957061, 2012). "This study explored the interaction of Anxa2 with P-Glycoprotein (P-gp) in the migration and invasion of the multidrug-resistant human breast cancer cell line MCF-7/ADR." (PMID 23691462, 2012). "Tyr23 phosphorylation of Anxa2 promotes the proliferation and invasion of human breast cancer SK-BR-3 cells and the phosphorylation of Stat3 in the nucleus." (PMID 23691485, 2012). "By contrast, the up-regulation of Anxa2 promotes the proliferation and invasion of breast cancer MCF-7 cells." (PMID 23691485, 2012). "Immunohistochemical expression analysis revealed a reciprocal regulation between Her-2 and AnxA2 in breast cancer clinical samples as well as in cell lines as confirmed by protein and RNA analysis." (PMID 22957061, 2012). "Our previous study demonstrates that the expression of Anxa2 increases when breast cancer MCF-7 cells acquire drug resistance (P-gp-over-expressing adriamycin-resistant breast cancer cells, denoted as MCF-7/ADR)." (PMID 23691462, 2012). "P-gp and Anxa2 proteins were also co-localized on the plasma membrane of multidrug-resistant breast cancer cells." (PMID 23691462, 2012). "In contrast, SK-BR-3 cells showed intense staining of Her-2 on the membrane compared to very weak staining of AnxA2, further supporting the reciprocal correlation between AnxA2 and Her-2 expression in breast cancer." (PMID 22957061, 2012). "An interaction between P-gp and Anxa2 is possibly responsible, at least in part, for the association between MDR and invasion/migration potentials in breast cancer cells." (PMID 23691462, 2012). "The present studies suggest important roles for AnxA2 and AnxA6 in exosomal mediated adhesion with implications in the progression of breast cancer." (PMID 21915303, 2011). "Accumulating evidence identifies ANXA2 as a pivotal biomarker for invasive breast cancer detection." (PMID 40234383, 2025). "Previously, p-glycoprotein (P-gp) was shown to bind ANXA2 and promote multidrug-resistant breast cancer invasion by regulating the phosphorylation of ANXA2, and further studies revealed that P-gp-mediated phosphorylation of ANXA2 is regulated by the receptor for activated C kinase 1 (RACK1)." (PMID 40234383, 2025). "Besides, ANXA2 can participate in the formation of various compounds to promote drug resistance in breast cancer." (PMID 38658569, 2024). "In HCC and breast cancer, ANXA2 was found to interact with FBXW7 and MIEN2 respectively." (PMID 38658569, 2024). "In breast cancer, blocking ANXA2 significantly inhibited neoangiogenesis." (PMID 37782406, 2024). "Our previous investigation demonstrated that annexin A2 helps reseal the injured plasma membrane, which accelerates cell migration and the invasion of breast cancer cells since the plasma membrane is exposed to severe physical stress that compromises cell dissemination movements." (PMID 37091157, 2023).
breast carcinoma (continued). "Furthermore, our present study discovered that AQP1 with ANXA2 and Rab1b formed a ternary complex in Golgi apparatus to induce breast cancer progression." (PMID 36803413, 2023). "Both in vivo assay and clinical analysis data confirmed that AQP1 could induce breast cancer progression by interacting with ANXA2 and Rab1b." (PMID 36803413, 2023). "In light of this interesting result, we suspected that the secreted LOXL4 may bind with cell-surface annexin A2 and catalyze it, resulting in integrin β-1 enrichment on the cell surface, which could work to promote the progression of breast cancer." (PMID 37091157, 2023). "In addition, the involvement of Anxa2 in angiogenesis has been highlighted in many malignancies, including aggressive breast cancer and glioblastoma." (PMID 37955107, 2023). "In addition, we have greatly increased our knowledge of the function of Annexin A2 in breast cancer cells, through interactome studies, contributing to the overall understanding of this protein." (PMID 37941562, 2023). "Furthermore, annexin A2 induced the activation of macrophages, favoring breast cancer metastasis in distant organs." (PMID 37893211, 2023). "Here, we show that the cytoplasmic water channel protein AQP1, a crucial target in breast cancer local invasion, recruited ANXA2 from the cellular membrane to the Golgi apparatus, promoted Golgi apparatus extension, and induced breast cancer cell migration and invasion." (PMID 36803413, 2023). "We investigated how modulations of the ECM may affect the role of Annexin A2 in MDA-MB-231 breast cancer cells using western blotting, immunofluorescent confocal microscopy and immuno-precipitation mass spectrometry techniques." (PMID 37941562, 2023). "In patients, we found Annexin A2 expression to be higher in aggressive, ER negative subtypes of breast cancer and to be associated with a higher risk of metastatic progression." (PMID 37941562, 2023). "Additionally, the amount of secreted AnxA2 was positively related to the aggressiveness of breast cancer cells." (PMID 36096820, 2022). "ANXA2 expression has been shown to promote proliferation, invasion and metastasis in gliomas, ovarian cancer, hepatomas, breast cancer and pancreatic cancer." (PMID 36247003, 2022). "The endoplasmic reticulum aminopeptidase 2 (ERAP2) has been identified by our group as an EpCAM‐associated protein, and here we continue this effort and present another novel finding that Annexin A2 (ANXA2) is a potential interacting partner of EpCAM in the EpCAM+ ERα+ breast cancer cells." (PMID 34240826, 2022). "In addition, high expression of exosomal AnxA2 levels in breast cancer was significantly correlated with tumor grade (p < 0.0001), poor OS (p = 0.0353), and DFS (p = 0.0301)." (PMID 35565189, 2022). "P-glycoprotein may promote the invasion of MDR breast cancer cells by modulating the tyrosine phosphorylation of ANXA2." (PMID 34048174, 2021). "In another study, phosphorylation at tyrosine 23 is required for ANXA2 activation, but knockdown of P-glycoprotein using small interference RNA in adriamycin-resistant breast cancer cell lines was found to significantly inhibit tyrosine phosphorylation of ANXA2." (PMID 34048174, 2021). "Previous studies have shown the expression of annexin A2 in circulating tumor cells of breast cancer patients and suggested that secreted forms of annexin A2 might play a role in coagulation activation." (PMID 33406648, 2021). "Ingenuity pathway analysis (IPA) revealed that the upregulated proteins hornerin (HRNR), tropomyosin alpha-1 chain (TPM1), annexin A (ANXA2), and protein-disulfide isomerase (PDI) were associated with breast or gynecological cancer, breast carcinoma, and inflammation of organ." (PMID 34771120, 2021). "Annexin A2 is related to angiogenesis and metastasis in breast cancer." (PMID 33668689, 2021).
breast carcinoma (continued). "In addition, exosomal ANXA2 promotes tPA-dependent angiogenesis, and depletion of exosomal ANXA2 decreases metastasis of breast cancer to the lung and brain." (PMID 34599143, 2021). "AnxA2 antibody-conjugated and curcumin-loaded nanoparticles effectively accumulated in tumours, providing sustained release of curcumin with potential to reduce metastatic breast cancer progression." (PMID 33810523, 2021). "Researches have shown that exosomal ANXA2 derived from breast cancer cells can not only promote angiogenesis in a tissue plasminogen activator (tPA) ‐dependent manner but also activate multiple signalling pathways and regulate the secretion of factors in macrophages." (PMID 34725902, 2021). "MDA-MB231 cells, unlike MCF-7 cells, had the ability to activate plasminogen, leading to the hypothesis that plasmin generating capacity correlates with breast cancer cell migration and aggressiveness, implicating AnxA2 as a key mediator in metastasis." (PMID 32575495, 2020). "ROC curves of serum exo-AnxA2 in breast cancer subtypes showed that AUC values of ER+, HER2+, and TNBC were 0.8304 ± 0.03843 (95% CI 0.7551–0.9058, P < 0.0001), 0.9958 ± 0.0029 (95% CI 0.9899–1.000, P < 0.0001) and 1.000 ± 0.000 (95% CI 1.000–1.000, P < 0.0001), respectively." (PMID 31992335, 2020). "In particular, ANXA2 overexpression correlates with poor prognosis in ovarian and breast cancer." (PMID 31936170, 2020). "The large sample size of the METABRIC analysis also revealed Annexin A2 to be upregulated in HER2 positive breast cancer, contradicting what has been previously published and suggesting the value of investigating Annexin A2 in breast cancer is not limited to the triple negative subtypes." (PMID 32629869, 2020). "In addition, the expression of exo-AnxA2 progressively increases with tumor grades of breast cancer patients (P < 0.0001)." (PMID 31992335, 2020). "ANXA2 has been detected by immunohistochemistry in ovarian and breast cancer." (PMID 31936170, 2020). "Taken together, this suggests that Annexin A2 is involved in processes that promote breast cancer disease progression and this could be particularly true for tumors driven by EGFR overexpression." (PMID 32629869, 2020). "When ANXA2 expression levels were stratified according to nodal involvement—an indicator of breast cancer disease progression—we found a trend of increased ANXA2 expression in those who had nodal positive disease, but this was not statistically significant (p = 0.8674, Mann Whitney U test)." (PMID 32629869, 2020). "The expression of exo-AnxA2 levels in serum samples of different breast cancer subtypes with tumor grades clearly suggests that the progressive increase of exo-AnxA2 levels seen in serum samples of breast cancer patients is specifically associated with TNBC subtypes of breast cancer." (PMID 31992335, 2020). "Exosomal or secreted Annexin A2 has been reported to promote breast cancer metastasis and angiogenesis in a number of studies and has even been proposed as a serum based biomarker for breast cancer detection." (PMID 32629869, 2020). "Additionally, exosomal-AnxA2 (exo-AnxA2) expression is significantly higher in malignant cells than normal and pre-metastatic breast cancer cells." (PMID 31992335, 2020). "Similarly, the median expression value of serum AnxA2 was used for DFS evaluation in breast cancer patients (n = 106) and divide into high AnxA2 (>9.208 ng/mL; n =53) and low AnxA2 (<9.208 ng/mL; n = 53) groups." (PMID 33374917, 2020). "Although overexpression of serum AnxA2 was also observed in breast cancer, the possible clinical and diagnostic significance of serum AnxA2 in breast cancer patients has not been reported at present." (PMID 33374917, 2020). "In patients, Annexin A2 expression is increased in ER- breast cancer subtypes." (PMID 32629869, 2020).
breast carcinoma (continued). "Notably, we found similar results with the serum samples of breast cancer patients, which illustrated as high circulatory level of AnxA2 in serum samples of TNBC patients compared to ER+, HER2+, and normal healthy females." (PMID 33374917, 2020). "Our data suggest that Anxa2 is an important co-activator of NF-κB in breast cancer cells." (PMID 32244350, 2020). "Therefore, this suggest that circulating serum AnxA2 levels can be used as an independent prognostic factor for breast cancer patients." (PMID 33374917, 2020). "Therefore, to elucidate the diagnostic value of serum AnxA2 in different breast cancer subtypes, ROC curve analysis based on serum AnxA2 levels of ER+, HER2+ and TNBC breast cancer patients compared to normal healthy patients was evaluated." (PMID 33374917, 2020). "Taken together, (20S)G-Rh2 targets Anxa2 in invasive breast cancer cells, inhibits NF-κB activity and EMT and may be a potent candidate for breast cancer treatment and related research." (PMID 32244350, 2020). "However, this requires further investigation as our result poses a challenge to the current general consensus that Annexin A2 is upregulated in breast cancer compared to pathologically normal tissue." (PMID 32629869, 2020). "However, lncRNA CCAT1, which is upregulated in breast cancer tissue and correlates with poor outcomes in breast cancer patients, was shown to interact with miR-204/211, miR-148a/152, and ANXA2." (PMID 32823855, 2020). "Although these previous studies revealed AnxA2 as an important player for breast cancer progression, the expression of AnxA2 protein in tumor tissues of different subtypes of breast cancer patients and its role as a secretory biomarker for breast cancer prognosis and diagnosis has not been studied." (PMID 33374917, 2020). "Increasing evidence suggests that AnxA2 contributes to invasion and metastasis of breast cancer." (PMID 33374917, 2020). "The serum AnxA2 levels in breast cancer patients and normal healthy females were analyzed by ELISA." (PMID 33374917, 2020). "Therefore, our goal was to examine the expression and function of exosomal-annexin A2 (exo-AnxA2) derived from the serum samples of breast cancer patients." (PMID 31992335, 2020). "Interestingly, we found that when unstratified breast cancer samples were compared to normal breast tissue, Annexin A2 expression was significantly lower in the cancer tissue." (PMID 32629869, 2020). "Therefore, comparison analysis of relative expression of exo-AnxA2 levels in serum samples of different breast cancer subtypes with tumor grade progression were performed." (PMID 31992335, 2020). "Surprisingly, despite several reports in the literature that ANXA2 is upregulated in breast cancer, we observed that expression of ANXA2 is significantly down regulated (p = 0.0002, Mann Whitney U test) in breast cancer tissue in comparison to pathologically normal breast tissue." (PMID 32629869, 2020). "Furthermore, our in vitro and in vivo studies demonstrated that exo-AnxA2 derived from breast cancer cells promotes angiogenesis." (PMID 31992335, 2020). "Furthermore, siRNA knockdown showed that Annexin A2 expression promotes the proliferation, wound healing and directional migration of breast cancer cells." (PMID 32629869, 2020). "Taken together, this data strongly supports the hypothesis that Annexin A2 promotes cell proliferation, wound healing and cell migration, all critical processes which support the malignant phenotype of ER- breast cancer cells in vitro." (PMID 32629869, 2020). "Taking into account the specificity we see of ANXA2 overexpression in ER-negative breast cancer and the potential influence ANXA2 has on disease progression in terms of lymph node involvement, we then wanted to ascertain the effect ANXA2 expression has on prognosis for breast cancer patients." (PMID 32629869, 2020).